MICAL1 (microtubule associated monooxygenase, calponin and LIM domain containing 1)
Diseases named in the same sentence as MICAL1 in open-access papers (continued):
Sharing a sentence is not in itself a finding about the gene and the disease.
gastric cancer (4 papers, 2019 to 2025). A primary or metastatic malignant neoplasm involving the stomach. "PlexinA1 interacts with the actin cytoskeleton regulator MICAL1 in a manner dependent on Rac1 and ROS, modulates vimentin expression, and prevents MICAL1 degradation, thereby facilitating gastric cancer cell migration." (PMID 41188920, 2025). "In all, these data suggested that by interaction with the MICAL1, NEDD9 maintained MICAL1 stability under hypoxia by reducing its degradation in gastric cancer cells." (PMID 31019460, 2019). "In all, it is concluded that MICAL1 is regulated by NEDD9 that facilitates hypoxia-induced gastric cancer cell migration via Rac1-dependent manner." (PMID 31019460, 2019). "So it is interesting to investigate the role of NEDD9 and MICAL1 in hypoxia-treated gastric cancer cells." (PMID 31019460, 2019). "Immunoblotting analysis showed that, in both gastric cancer cells, the amount of MICAL1 was increased significantly after hypoxia incubation with maximal activation at 4 h, and it declined toward basal levels after 8 h." (PMID 31019460, 2019). "In all, we identified a novel link between NEDD9 and MICAL1 in accelerating gastric cancer cell motility under hypoxia." (PMID 31019460, 2019). "MICAL1 plasmid significantly increased the MICAL1 expression in gastric cancer cells, confirming the efficiency of the MICAL1 overexpression protocol in the present study." (PMID 31019460, 2019). "Under hypoxic conditions, silencing of NEDD9 caused reduction in the stability of MICAL1 protein, while depletion of MICAL1 also inhibited the migration of NEDD9-overexpressing gastric cancer cells." (PMID 31019460, 2019). "It suggests the possibility that MICAL1 participated in the control of gastric cancer cell migration." (PMID 31019460, 2019). "In the present work, we observed that NEDD9 bound directly to MICAL1 in gastric cancer cells and this interaction increased under hypoxic condition." (PMID 31019460, 2019). "Knockdown of either NEDD9 or MICAL1 in gastric cancer cells inhibited hypoxia-induced ROS production." (PMID 31019460, 2019). "In contrast, MICAL1 deletion inhibited NEDD9-mediated migration in gastric cancer cell lines." (PMID 31019460, 2019). "Furthermore, knockdown of MICAL1 repressed the hypoxia-promoted gastric cancer cell migratory phenotype." (PMID 31019460, 2019). "Therefore, it was identified that hypoxia-induced NEDD9 expression has the ability to maintain MICAL1 protein level by reducing its degradation, thereby maintaining gastric cancer cell migratory properties." (PMID 31019460, 2019). "Based on the finding that NEDD9 interacts with MICAL1 by far western screening, we further investigated whether MICAL1 was also involved in hypoxia-stimulated gastric cancer cell migration." (PMID 31019460, 2019). "However, least data are available about the relationship between NEDD9 and MICAL1 in gastric cancer cells." (PMID 31019460, 2019). "However, only the upregulation of Rac1-GTP level was observed in gastric cancer cells that were already overexpressed by MICAL1." (PMID 31019460, 2019). "Collectively, these results revealed that NEDD9/MICAL1 may act on Rac1 to affect hypoxia-induced gastric cancer cell migration." (PMID 31019460, 2019). "In vitro, hypoxia induced MICAL1 protein level in a time-dependent fashion in gastric cancer cells." (PMID 31019460, 2019). "Unfortunately, the regulator(s) of MICAL1 in gastric cancer is still unclear." (PMID 31019460, 2019). "The result suggests a possibility that the upregulation of NEDD9 may contribute to the MICAL1 expression in gastric cancer cells." (PMID 31019460, 2019). "Furthermore, we observed that hypoxia stimulated Rac1 activation, which may serve as an important mediator for NEDD9/MICAL1-facilitated gastric cancer cell migration." (PMID 31019460, 2019). "Interestingly, only Rac1 activity was increased in MICAL1-overexpressed gastric cancer cells." (PMID 31019460, 2019).
gastric cancer (continued). "Therefore, it is understood that MICAL1 might stimulate Rac1 activation via PI3K/Akt signaling in gastric cancer cells." (PMID 31019460, 2019). "By analysis of gastric cancer specimens, we noticed a positive correlation between NEDD9 and MICAL1 protein expressions." (PMID 31019460, 2019). "The results here demonstrated that hypoxia promoted gastric cancer cell migration by positively regulating the expression of NEDD9 and its subsequent binding to MICAL1." (PMID 31019460, 2019). "Immunohistochemistry analysis in the gastric cancer tissue microarray showed a positive correlation between NEDD9 and MICAL1 expressions (r = 0.55)." (PMID 31019460, 2019). "It is reported that NEDD9 overexpression correlates with poor prognosis of gastric cancer, However, in our study, due to the limited number of samples, we were unable to demonstrate the significant interaction between NEDD9, MICAL1, and gastric cancer progression (data not shown)." (PMID 31019460, 2019).
colorectal cancer (2 papers, 2022). A primary or metastatic malignant neoplasm that affects the colon or rectum. "While low expression of MICAL1 was found in colorectal cancer (CRC), and silencing of MICAL1 promoted CRC cell migration and enhanced EMT, the results from bioinformatic analysis strongly suggested that MICAL1 was a cancer-promoting gene in KIRC." (PMID 36575439, 2022).
pancreatic cancer (2 papers, 2022 to 2024). "Thus, MICAL1 is a potential therapeutic target for improving the clinical prognosis of patients with pancreatic cancer." (PMID 36371204, 2022). "However, to date, the role of MICAL1 in the pathogenesis and progression of PC has rarely been reported, whether MICAL1 could be a potential therapeutic target for pancreatic cancer is still unclear." (PMID 36371204, 2022). "MICAL1 is involved in the malignant processes of several types of cancer; however, the role of MICAL1 in pancreatic cancer (PC) has not been well-characterized." (PMID 36371204, 2022).
tauopathies (2 papers, 2022). "Moreover, the protein level of Mical1 was increased in AD patients, and considered to be a potential biomarker of tauopathies." (PMID 36006403, 2022). "Importantly, we also validate results from the fly model in human Tauopathy samples by showing that MICAL1 is up-regulated in patient brains and co-localizes with Tau in Pick bodies." (PMID 35379354, 2022). "The novel effects of Mical on Tau-mediated toxicity and dysfunction in the fly Tauopathy model suggested that the levels or localization of the human Mical orthologue MICAL1 may in fact be altered in Tauopathy patients compared to non-demented controls." (PMID 35379354, 2022). "The importance of the Tau-Mical interaction as a novel molecular mechanism underlying the development of Tau pathology has been reinforced by the finding that human MICAL1 is up-regulated in brain tissue samples from individuals with Tauopathies as compared to non-demented controls." (PMID 35379354, 2022).
breast tumor (1 paper, 2022). "The disruption of MICAL1 activity was shown to impair cytoskeleton organization and breast tumor growth in an orthotopic model." (PMID 35501725, 2022).
clear cell carcinoma (1 paper, 2022). "The in vitro study showed that knockdown of MICAL1 led to a decreased Rac1 activation and migration of clear cell carcinoma cells." (PMID 36575439, 2022).
diabetes (1 paper, 2022). "Except for the completely restored DEGs, Sal treatment mitigated the expression of approximately 73.08% up-regulated DEGs and 66.35% down-regulated DEGs induced by diabetes, including 8 oxidation-related genes (Aldh4a1, Acad12, Ado, Kdm4d, Acacb, Mical1, Th and Htatip2)." (PMID 35370972, 2022).
epilepsy (1 paper, 2022). A brain disorder characterized by episodes of abnormally increased neuronal discharge resulting in transient episodes of sensory or motor neurological dysfunction, or psychic dysfunction. "MICAL-1 expression was downregulated in TLE patients and a pilocarpine-induced rat model of epilepsy." (PMID 36044155, 2022).
oral squamous cell carcinoma (1 paper, 2019). "Recent study highlighted that MICAL1 deficiency in oral squamous cell carcinoma arrested MMP9 secretion, vimentin, and E-cadherin levels, consistent with increased N-cadherin." (PMID 31019460, 2019).
prostate carcinoma (1 paper, 2023). A carcinoma that arises from epithelial cells of the prostate gland. "MICAL1 has not been studied in prostate cancer but variants of MICAL2 have progression promoting role in prostate cancer." (PMID 36809527, 2023).
psoriasis (1 paper, 2024). An autoimmune condition characterized by red, well-delineated plaques with silvery scales that are usually on the extensor surfaces and scalp. "Flow cytometry analysis also showed that γδ T cells from IMQ-induced psoriasis mice had higher levels of MICAL1 and MICAL2 expression." (PMID 38566145, 2024).
pulmonary TB (1 paper, 2016). "Therefore, the down-regulation of MICAL1 may be related to pulmonary TB via controlling cell migration and phagocytosis." (PMID 27655333, 2016).
renal carcinoma (1 paper, 2022). A carcinoma arising from the epithelium of the renal parenchyma or the renal pelvis. "Unlike the results obtained in KIRC, high expression of MICAL1 was not significantly correlated with poor OS in the other two kinds of renal carcinoma, KICH (p = 0.171) and KIRP (p = 0.728)." (PMID 36575439, 2022).
renal clear cell carcinoma (1 paper, 2022). "To analyze the role of MICAL1 in the progression of renal clear cell carcinoma, we performed MICAL1 loss-of-function assays in renal clear cell carcinoma cells." (PMID 36575439, 2022). "We only checked the migratory and proliferative abilities of renal clear cell carcinoma cells after silencing MICAL1 in those cells." (PMID 36575439, 2022). "These in vitro experiments were too preliminary to depict the potential functions of MICAL1 in renal clear cell carcinoma." (PMID 36575439, 2022). "Together, the results suggested the role of MICAL1 in promoting migratory ability of renal clear cell carcinoma cells." (PMID 36575439, 2022). "However, there were few reports on the clinical significance of MICAL1 in renal clear cell carcinoma." (PMID 36575439, 2022). "MICAL1 expression may act as a prognostic biomarker for determining the prognosis in renal clear cell carcinoma and plays an important role in regulating tumor immune microenvironment and cell migratory capacity." (PMID 36575439, 2022). "The expression and prognostic value of MICAL1 in renal clear cell carcinoma were explored using immunohistochemical assays, public TCGA-KIRC databases and multiple analysis methods, including survival analysis, univariate and multivariate analyses, KEGG and GSEA." (PMID 36575439, 2022).
cancer (15 papers, 2016 to 2025). A tumor composed of atypical neoplastic, often pleomorphic cells that invade other tissues. "MICAL1 was first discovered in 2002 and it is increasingly being implicated in various pathologies, including different cancers, diabetic nephropathy, susceptibility to infection, epilepsy, and cardiac protection." (PMID 36371204, 2022). "MICAL1 is well characterized in the ROS generation, which has been associated with cancer cell invasion." (PMID 27430308, 2016). "An examination of cancer-associated MICAL1 mutations suggests that there may be both activating and inactivating mutations, although the biochemical characterization of the consequences of these mutations is lacking." (PMID 35627100, 2022). "The effect of these mutations on MICAL1 activity would have to be characterized in order to determine whether MICAL1 gain or loss of function is the predominant consequence of cancer-associated mutations." (PMID 35627100, 2022). "We also consider whether these types of activating MICAL1 mutations could be linked to cancer." (PMID 35627100, 2022). "In cancer, altered MICAL expression, particularly MICAL1 and MICAL2, appears to play a crucial role in disease progression and metastasis." (PMID 40328105, 2025). "So, combined with the characteristic of cargo transportation, recent evidence revealed the role of MICAL1 in carcinogenic biological processes, including cancer cell proliferation, invasion, and survival regulation." (PMID 36575439, 2022). "Molecule interacting with CasL 1 (MICAL1), a multidomain flavoprotein monooxygenase, is strongly involved in the biological processes related to cancer cell proliferation and metastasis." (PMID 36575439, 2022). "MICAL1 has been found overexpressed in several types of human cancers, including pancreatic adenocarcinoma and melanoma." (PMID 36575439, 2022). "A key depolymerizer of actin filaments also found in a hypomethylated region in PE is MICAL1, which regulates actin cytoskeleton dynamics in a variety of processes from cytokinesis to invasion and mobility in cancer." (PMID 34941772, 2021). "Combined with the characteristic of anti-apoptosis, MICAL1 has been proven to be involved in cancer cell growth and survival regulation." (PMID 27430308, 2016). "Molecules Interacting with CasL (MICAL1), a multidomain flavoprotein monoxygenase, is strongly involved in the mechanisms that promote cancer cell proliferation and survival." (PMID 27430308, 2016). "While most studies suggested its relationship with the advancement of cancer, a few also indicated that MICAL1 may play a role in neural development following spinal cord injury, and the occurrence of lateral temporal epilepsy." (PMID 39953802, 2025). "MICAL1 expression in various types of cancers was also investigated in the TCGA database." (PMID 36575439, 2022). "Copy number variations were detected in 373 tumor samples, of which 180 were amplifications and 193 were deep deletions, suggesting that there may be cancer-specific contexts that favor increased or decreased MICAL1 activity." (PMID 35627100, 2022). "In addition, we evaluated the role of MICAL1 in migration capacity of reanl cancer cells using functional assays." (PMID 36575439, 2022). "Consistently, MICAL1 overexpression in the cancer cells accelerated their motility behavior." (PMID 27430308, 2016). "This suggests that MICAL1 could have similar tumor promoting roles in PCa than in other cancers." (PMID 36809527, 2023). "Thus, increased MICAL1 activity could be involved in cancer progression through its effects on the cytoskeleton and increased ROS production." (PMID 35627100, 2022). "NEDD9 was identified to interact with MICAL1 by far western screening analysis providing a basis for further exploring the role of MICAL1 in NEDD9-induced alteration of cancer cell function." (PMID 31019460, 2019).
cancer (continued). "MICAL1 has the most closely related domain architecture to Drosophila MICAL, however, to date, only a few reports have been published to describe the functions of MICAL1 during cancer progression." (PMID 27430308, 2016). "MICAL1 expression was significantly higher in carcinoma tissue compared with non-cancerous tissue." (PMID 36575439, 2022). "Endothelial cells (ECs) of neo-angiogenic capillaries that extensively branch into the cancer mass showed a very intense MICAL2 immunostaining, but no expression of MICAL1 and MICAL3, suggesting a different role of MICAL proteins within neo-angiogenic ECs." (PMID 26689989, 2016).
tumor (8 papers, 2012 to 2024). "Cox multivariate analysis showed that MICAL1 expression was an independent risk factor for tumor progression (p = 0.007)." (PMID 36575439, 2022). "Given that H2O2 is produced by MICAL1, increased MICAL1 activity resulting from point mutations such as G150S truncating mutations, or mutations such as A1065fs that disrupt the autoinhibitory actions of the C-terminal region, could be tumor-promoting." (PMID 35627100, 2022). "Interestingly, one G150S point mutation was detected in an endometrial carcinoma tumor sample, suggesting that MICAL1 activation could be tumor-promoting in this case." (PMID 35627100, 2022). "Conversely, MICAL1 expression is negatively correlated with γδ T cells, natural regulatory T cells (nTreg), natural killer cells (NK), central memory T cells, and Th17 cell infiltration, which typically possess anti-tumor functions." (PMID 38995414, 2024). "Therefore, by multiple databases, we explored the expression, prognosis, as well as tumor infiltrating lymphocytes of the MICAL1 in KIRC." (PMID 36575439, 2022). "The subcutaneous tumorigenesis model and the caudal vein pulmonary metastasis model were constructed with PANC-1 cells to investigate whether MICAL1 played a role in tumor formation and metastasis in vivo." (PMID 36371204, 2022). "Overall, our results indicated that MICAL1 played a tumor-promoting role in PC." (PMID 36371204, 2022). "In this study, we found that MICAL1 expression was distinctly increased in many types of tumors, including AML, suggesting it as a tumor promotor." (PMID 38995414, 2024). "Since an important function of MICAL1 is F-actin depolymerization, and there are many biological processes that depend on the actin cytoskeleton, there may be specific situations or cell types in which either increased or decreased MICAL1 activity is tumor-promoting." (PMID 35627100, 2022). "We further explore the possible cellular mechanism of MICAL1 through the Kyoto Encyclopedia of Genes and Genomes (KEGG), Gene Set Enrichment Analysis (GSEA), and Tumor IMmune Estimation Resource (TIMER), TISIDB analysis." (PMID 36575439, 2022). "The overexpression of MICAL1 and RABAC1 is likely due to the presence of stromal cells in the tumor as MICAL1 is highly expressed in different types of hematopoietic cells (dendritic cells, mast cells and NK cells) and RABAC1 in mast cells (data not shown)." (PMID 22724020, 2012). "Finally, we concluded our functional tests by showing that MICAL1 knockdown markedly reduced AML cell proliferation, providing further evidence for its role as a tumor promotor in AML." (PMID 38995414, 2024).
infection (1 paper, 2025). The state of being infected such as from the introduction of a foreign agent such as serum, vaccine, antigenic substance or organism. "Nevertheless, the enhanced suppression of MICAL1 and P-ERK upon the infection in Trem2−/− mice indicates that Trem2 likely plays a critical protective role during the infection, alleviating the parasite’s ability to over-suppress MICAL1/P-ERK signaling." (PMID 41305343, 2025).
MICAL1 also shares sentences with these, for which no sentence is quoted: acute myeloid leukemia (1 paper); amyotrophic lateral sclerosis (1); bladder cancer (1); deafness (1); endometrial carcinoma (1); Hypertension (1); latent infection (1); metabolic syndrome (1); Thromboembolism (1); Von Willebrand disease (1).